TMEM230 (transmembrane protein 230)
Description:
Involved in trafficking and recycling of synaptic vesicles.
Synonyms: C20orf30; HSPC274; dJ1116H23.2.1
Tractability: Antibody: UniProt predicts a signal peptide or a membrane-spanning region. PROTAC: ubiquitination databases record sites on it; its protein half-life has been measured.
Gene: Protein-coding gene on chromosome 20 (5,068,232 to 5,113,452, reverse strand). Ensembl gene ENSG00000089063.
Subcellular location: Membrane; Golgi apparatus, trans-Golgi network; Cytoplasmic vesicle, secretory vesicle, synaptic vesicle; Early endosome; Recycling endosome; Late endosome; Cytoplasmic vesicle, autophagosome
Subcellular location (Human Protein Atlas): Endoplasmic reticulum
Gene Ontology:
Biological process: axonal transport; synaptic vesicle transport
Cellular component: early endosome; late endosome; recycling endosome; synaptic vesicle; trans-Golgi network; endomembrane system; autophagosome; axon; Golgi apparatus; membrane
Genetic constraint (gnomAD): Loss-of-function variants: 8 observed, 11.24 expected, observed/expected ratio (o/e) 0.71, 90% interval 0.42 to 1.28. The upper end of that interval is the gene's LOEUF score, 1.28, which puts it in group 5 of 6, group 1 being the genes least tolerant of losing a copy. Missense variants: 162 observed, 179.41 expected, observed/expected ratio (o/e) 0.9, 90% interval 0.79 to 1.03. Synonymous variants: 67 observed, 72.76 expected, observed/expected ratio (o/e) 0.92, 90% interval 0.75 to 1.13.
Homologues: Orthologues: chimpanzee TMEM230 (100% identical), macaque TMEM230 (100% identical), guinea pig TMEM230 (99% identical), dog TMEM230 (98% identical), mouse Tmem230 (97% identical), tropical clawed frog tmem230 (88% identical), zebrafish tmem230a (76% identical), zebrafish tmem230b (74% identical), Drosophila melanogaster CG2611 (28% identical).
Diseases named in the same sentence as TMEM230 in open-access papers:
TMEM230 is named in the same sentence as 23 diseases in open-access papers, as found by Europe PMC text mining. Sharing a sentence is not in itself a finding about the gene and the disease. The quoted sentences say what the papers report.
Parkinson disease (14 papers, 2016 to 2025). A progressive degenerative disorder of the central nervous system characterized by loss of dopamine producing neurons in the substantia nigra and the presence of Lewy bodies in the substantia nigra and locus coeruleus. "In support of the candidate role of TMEM230 in aging, mutated forms of the TMEM230 gene were previously identified in the development of many neurodegenerative disorders associated with aging, including Alzheimer’s and Parkinson’s diseases." (PMID 40141059, 2025). "Concurrent with our studies, specific human gene mutations were discovered, which may drive aberrant TMEM230 protein structure formation in Parkinson’s disease (PD) and Alzheimer’s disease (AD)." (PMID 40141059, 2025). "Parkinson’s disease (PD) patient specific variants of TMEM230." (PMID 35860667, 2022). "Finally, additional investigation is required to identify the effect of RME-8 in familial Parkinson's disease, and to determine whether its dysfunction works independently or synergistically with the mutation in TMEM230 to influence disease progression." (PMID 28579939, 2017). "An independent study in the same Mennonite kindred identified the c.422G>T variant in TMEM230 (Transmembrane protein 230, MIM*617019) as the cause of the Parkinsonism segregating in that family." (PMID 34630269, 2021). "Furthermore, numerous genes have recently been implicated in Parkinson’s disease, such as CHCHD2, LRP10, TMEM230, UQCRC1, and VPS13C." (PMID 35328025, 2022). "In particular, we envisage that more detailed investigations on experimental models of GBA1-, SYNJ1-, SYPH1-, TMEM230-, Parkin-, PINK1-, ATP13A2-, FBXO7- and SYT11-associated parkinsonism could provide new insight into the pathophysiological mechanisms leading to PD that may involve Rab dysfunction." (PMID 36009486, 2022). "Unlike the chronic course of Parkinson’s disease, acute neurological disorders may be more intense in terms of neuronal stress, and the role of TMEM230 in this remains to be further investigated in depth." (PMID 37901436, 2023).
glioblastoma (4 papers, 2021 to 2025). The most malignant astrocytic tumor (WHO grade IV). "Gene expression analysis uncovered specific pathways associated with the increase of TMEM230 expression in LGG and glioblastoma from patients." (PMID 34867197, 2021). "Highest levels of TMEM230 were correlated in glioblastoma with ribosome generation, mitochondria ATP synthesis, kinesin motor proteins, ATP synthesis and ATP dependent microtubule motor activity." (PMID 34867197, 2021). "Highest level of TMEM230 correlated with glioblastoma and ATP-dependent microtubule kinesin motor activity, providing a direction for future therapeutic intervention." (PMID 34867197, 2021). "TMEM230 promoted the malignant process of glioblastoma by promoting tumor angiogenesis." (PMID 38850316, 2024). "Downregulation of TMEM230 expression may inhibit both low grade glioma and glioblastoma tumor progression and promote normalization of abnormally formed blood vessels." (PMID 34867197, 2021). "For instance, secreted factors and vesicles from U87-MG cells (a glial cell line model of glioblastoma multiforme, GBM) expressing TMEM230 have the capacity to promote endothelial cell sprouting and proliferation." (PMID 38612777, 2024). "Moreover, molecular tumor and angiogenic pathways identified with TMEM230 may help develop novel therapeutic strategies for inhibiting migration, abnormal tumor microenvironment and blood vessel remodeling of tumor glial cells, and tumor driven angiogenesis of glioblastoma cells." (PMID 34867197, 2021). "As the formation of new blood vessels is necessary for tumor expansion, the expression level of TMEM230 was evaluated in several types of human glial tumors to establish whether TMEM230 expression discriminates glioblastoma multiforme (GBM) from lower grade glial (LGG) tumors." (PMID 34867197, 2021).
glioma (4 papers, 2021 to 2025). A benign or malignant brain and spinal cord tumor that arises from glial cells (astrocytes, oligodendrocytes, ependymal cells). "Collectively, patient-derived tumor expression analysis supported that a high level of TMEM230 was associated with high-grade infiltrating and more aggressive gliomas (in terms of patient survival and tumor grade)." (PMID 38612777, 2024). "This suggested that high expression of TMEM230 promoted glycoprotein-associated angiogenesis in highly vascularized infiltrating gliomas." (PMID 38612777, 2024). "In conclusion, the tumor properties associated with glioma patients are supportive of the functional tumor role of TMEM230 demonstrated in the U87 and HUVEC assays performed in this study." (PMID 34867197, 2021). "Of interest was to determine which genes and pathways may be promoted by elevated levels of TMEM230 in the progression from low- to high-grade gliomas and whether these genes and pathways were associated with angiogenesis or microchannel formation." (PMID 38612777, 2024). "As we previously identified that many of these pathways in gliomas of patients were associated with aberrant expression of TMEM230 and RNASET2, in our current study we investigated whether these pathways would also be identified in fibroblast clusters of HER2+ breast cancer patients." (PMID 40862725, 2025). "Progress in glioma research would greatly benefit in understanding which pathways regulated by TMEM230 in endothelial and glial cells contribute to de novo formation of defective blood vessels or vascular mimicry in highly vascularized tumors." (PMID 38612777, 2024). "Collectively, the results of the infiltrating astrocytoma cells support that TMEM230 is regulator of glial cell vascular mimicry and endothelial cell angiogenesis in diverse high-grade infiltrating gliomas, including ODG and astrocytoma." (PMID 38612777, 2024). "There was also a clear transition in changes in glial tumor cellular activity with increasing levels of TMEM230 as shown with GBM and LGG pathways being different except for exosome and extracellular matrix pathways." (PMID 34867197, 2021). "Our studies support that TMEM230 has both glial tumor and endothelial cell intracellular and extracellular functions." (PMID 34867197, 2021). "Collectively, expression analysis of GBM and LGG identified candidate pathways regulated by TMEM230 in glial tumor formation." (PMID 34867197, 2021). "Within low grade gliomas, elevated TMEM230 expression levels correlated with reduced overall survival independent from tumor subtype." (PMID 34867197, 2021). "Gene expression analysis of 702 patients identified that TMEM230 expression levels distinguished high from low grade gliomas." (PMID 34867197, 2021). "Here we propose that aberrantly elevated levels of TMEM230 promote abnormal vascularization by driving endothelial cells to generate an abundance of defective blood vessels or glial tumor cells to form vessel like structures through VM." (PMID 34867197, 2021). "These analyses provide strong support that TMEM230 function uncovered in U87 regulate the tumor processes of cell attachment, migration and secretion in glioma formation and progression." (PMID 34867197, 2021). "Elevated levels of TMEM230 promote glial tumor cell migration, extracellular scaffold remodeling, and hypervascularization and abnormal formation of blood vessels." (PMID 34867197, 2021). "Our results may support that TMEM230 likely regulates various cell types in heterogeneous infiltrating gliomas by modulating microchannel-forming glial cells and blood-vessel-forming endothelial cells and these activities likely overlap." (PMID 38612777, 2024). "We hypothesized that elevated levels of TMEM230 drive both glioma (or macrophage) cell infiltration through microchannel formation and endothelial cell sprouting for blood vessel formation." (PMID 38612777, 2024).
glioma (continued). "Determining whether other glioma cell types, such as astrocytoma, have similar pathways modulated with TMEM230 expression levels would provide further evidence that TMEM230 may be a cancer target for glioma treatment." (PMID 38612777, 2024). "Expression data were used to determine whether TMEM230 was also differentially expressed in glial tumor tissue cells from patients with low- or high-grade ODG or GBM." (PMID 38612777, 2024). "Validation of candidate targets of TMEM230 activity was performed by determining whether genes identified differentially expressed in gliomas were modulated with downregulation of TMEM230 in U87 cells." (PMID 34867197, 2021). "Moreover, TMEM230 drives glial tumor cells to promote abnormal tissue and existing blood vessel remodeling." (PMID 34867197, 2021). "Additionally, we evaluated whether TMEM230 expression correlated the specific glioma tumor subtypes, astrocytoma (top), oligoastrocytoma (middle) and oligodendroglioma (bottom)." (PMID 34867197, 2021). "Collectively, the pathways correlated with different TMEM230 expression levels identified from LGG patient and high-grade glioma GBM support the functional cellular behavior observed in the U87 cell assays in which TMEM230 expression was modulated." (PMID 34867197, 2021). "Aggressive high-grade gliomas are highly vascularized with permeable and defective blood vessels that result in tissue hypoxia, necrosis, and cell death, suggesting that TMEM230 may be upregulated in part due to lack of oxygen." (PMID 38612777, 2024). "Search of published and open access research on microarray, sequencing and proteomic expression analyses did not uncover any datasets to evaluate whether TMEM230 was differentially expressed specifically between non-malignant glial cells and glial cells from low- or high-grade gliomas." (PMID 34867197, 2021). "When gene expression analysis was performed comparing high-grade gliomas (GBM) with all low-grade glioma (LGG) subtypes combined and independent of the level of TMEM230, pathways identified with high and low TMEM230 were a subset, as expected." (PMID 34867197, 2021).
astrocytoma (2 papers, 2021 to 2024). "As for U87-MG cells, infiltration and microchanneling were inhibited with the ablation of TMEM230 in astrocytoma cells." (PMID 38612777, 2024). "The genes and pathways identified as being regulated by TMEM230 were supported by the astrocytoma cell functional assays." (PMID 38612777, 2024). "The genes and pathways identified regulating infiltration and microchanneling that were modulated with TMEM230 expression were similarly identified in astrocytoma as they were for ODG." (PMID 38612777, 2024). "TMEM230 was significantly differentially expressed between LGG astrocytoma compared to HGG astrocytoma (a base mean expression of 1872.54 in LGG tumors, and a log2 fold change of 0.695271080072909 associated with an adjusted p-value of 9.14930075327835 × 10−74)." (PMID 38612777, 2024).
Autoimmunity (2 papers, 2025). The occurrence of an immune reaction against the organism's own cells or tissues. "Likely, the downregulation of TMEM230 observed in RA and concomitant misregulation of enzymes in glycolysis in RA may represent a paradigm for the study of other autoimmune disorders associated with aging." (PMID 40141059, 2025). "The role of TMEM230 in autoimmunity is also supported by our previous study of GCA, a disorder of immune system dysfunction often observed in older patients." (PMID 40141059, 2025). "For instance, IFN alpha and gamma regulate ER dependent function in antigen presentation, suggesting that the TMEM230/RNASET2/SDC2/IRF1 axis is mis regulated both in autoimmunity and cancer." (PMID 40862725, 2025). "Our results supported TMEM230 may represent a key target for therapeutic intervention in other autoimmunity disorders and cancers through its role in regulating the expression of enzymes in glycan synthesis and processing and glycolysis." (PMID 40141059, 2025). "This suggests that TMEM230 may have a central role in the metabolization of toxic compounds in autoimmunity or aging." (PMID 40141059, 2025). "TMEM230, as a regulator of metabolization of toxic compounds or drugs, has important implications for promoting or inhibiting autoimmune disorders, where a toxic environment may have an input in increasing the risk factor in pathogenesis." (PMID 40141059, 2025). "In support that TMEM230 may have a role in autoimmunity, TMEM230 was detected as downregulated in synovial tissue cell types from patients with RA compared to OA by single cell transcriptomic sequencing analysis )." (PMID 40141059, 2025). "TMEM230, RNASET2 and IFNs regulate antigen processing, trafficking and presentation in autoimmunity." (PMID 40862725, 2025). "We propose that the downregulation of TMEM230 and RNASET2 may represent a paradigm for the study of age-dependent autoimmune disorders due to their role in regulating glycosylation, unfolded protein response, and PI3K-AKT-mTOR signaling." (PMID 40141059, 2025).
Neurodegeneration (2 papers, 2022 to 2025). Progressive loss of neural cells and tissue. "Concurrent with our TMEM230-associated studies, specific human gene mutations were identified promoting aberrant TMEM230 protein structure formation in age-dependent neurodegeneration disorders, including Parkinson’s disease (PD) and Alzheimer’s disease (AD)." (PMID 40141059, 2025).
oligodendroglioma (2 papers, 2021 to 2024). A well-differentiated (WHO grade II), diffusely infiltrating neuroglial tumor, typically located in the cerebral hemispheres. "This creates a tumor tissue microenvironment that is hypoxic, resulting in both tissue necrosis and cell death, in agreement with the lower patient survival associated with higher levels of TMEM230 in oligodendroglioma and GBM." (PMID 38612777, 2024). "As GBM has predominantly higher levels of TMEM230 compared to both LGG and HGG oligodendroglioma, this suggests that even low TMEM230 expression in GBM is sufficiently high to induce high patient mortality." (PMID 38612777, 2024). "Even the lowest levels of TMEM230 in GBM corresponded to the high levels of HGG oligodendrogliomas." (PMID 38612777, 2024). "Patients with GBM expressed the highest levels of TMEM230 and the lowest survivability when compared to patients with LGG or HGG oligodendroglioma." (PMID 38612777, 2024). "Our results support that TMEM230 may be a regulator in the formation of the invasive and infiltrating behavior observed in diverse and heterogenous cell types in HGG oligodendroglioma and GBM." (PMID 38612777, 2024). "As the TMEM230 expression of HGG oligodendroglioma corresponded with low survivability for patients, not surprisingly, low survival was also correlated with GBM." (PMID 38612777, 2024).
rheumatoid arthritis (2 papers, 2025). A chronic, systemic autoimmune disorder characterized by inflammation in the synovial membranes and articular surfaces. "We previously demonstrated that TMEM230 and RNASET2 were downregulated in CXCL12 expressing synovial fibroblast cells of rheumatoid arthritis (RA) compared to osteoarthritis (OA) patients." (PMID 40862725, 2025).
breast carcinoma (1 paper, 2025). "Pathways identified in CXCL12 and FB2 fibroblast cell clusters from RA and in the B2 cell cluster from HER2+ breast cancer patients support that TMEM230/RNASET2/SDC2/IRF1 axis have pleiotropic functions." (PMID 40862725, 2025). "In this study, we identified expression patterns of IRF1, TMEM230, RNASET2, and syndecan 2 (SDC2) in different cell types of breast cancer patients using single-cell mRNA transcript analyses." (PMID 40862725, 2025).
giant cell arteritis (1 paper, 2025). "We previously identified that patients with age-associated disorders such as giant cell arteritis expressed lower levels of TMEM230 in blood vessels and in peripheral blood immune cells." (PMID 40141059, 2025).
macular degeneration (1 paper, 2021). Loss of vision in the central portion of the retina (macula), secondary to retinal degeneration. "Modulation of TMEM230 may have applications in addition to cancer treatment, for instance disorders in which unregulated angiogenesis results in unwanted new blood vessel formation such as in macular degeneration." (PMID 34867197, 2021).